IL7 (interleukin 7)
Diseases named in the same sentence as IL7 in open-access papers (continued):
Sharing a sentence is not in itself a finding about the gene and the disease.
tumor (continued). "Studies have shown anti-tumor benefits for using IL-15 as well as IL-7 in culture or IL-15 genetically engineered into T cells with CAR synchronously." (PMID 36167591, 2022). "Then, we evaluated the efficacy of HSV-2 vectors expressing IL-12, IL-15, PD-1v, GM-CSF, and IL7 × CCL19 using syngeneic CT26 tumor-bearing model." (PMID 35459242, 2022). "On the other hand, evidence has shown that the administration of IL-7/IL-7Rα-Fc inhibits tumor growth and prolongs survival in lung cancer by inducing afferent and efferent antitumor responses." (PMID 35794603, 2022). "These collected facts highly indicated that IL-7 acts as a tumor-promoting factor during the occurrence and progression of hematopoietic malignancy." (PMID 36389666, 2022). "The anti-tumor cytotoxic and antimicrobial effects of monocytes/macrophages treated with IL-7 have also been described." (PMID 34925323, 2021). "Human interleukin-7 (IL-7) is a pleiotrophic cytokine with a wide range of immune effects, which exhibits a direct or indirect role in the anti-tumor effect; it can also affect the growth, survival, and differentiation of B and T cells." (PMID 34778046, 2021). "We previously demonstrated that intratumoral expression of IL-7 and IL-12 increased tumor-infiltrating lymphocytes in poorly immunogenic tumors, resulting in a higher tumor regression rate than IL-12 alone." (PMID 33909103, 2021). "A group of researchers demonstrated that therapy using an IL-7 complex, formed with an IL-7R-Fc, induced anti-tumor responses by increasing tumor infiltration of T cells through CXCR3 chemokine signaling." (PMID 34925323, 2021). "Other studies have demonstrated the increased anti-tumor efficacy of combination chemotherapy and IL-12, IL-7, IFN-γ, and IFN-α immunocytokines." (PMID 33803078, 2021). "We demonstrated a critical role for type I IFN signaling in negatively controlling IL-7-dependent accumulation of γδT17 cells in the tumor bed." (PMID 34298791, 2021). "TH2-induced tumorigenesis is further driven by their expression of IL-7, which can act as a pro-angiogenic factor, resulting in leaky vasculature and allowing the tumor microenvironment to expand and migratory tumor cells to enter the surrounding tissue." (PMID 34012451, 2021). "As expected, rhIL-2 or IL7-Fc alone suppressed tumor growth rates, but which was further suppressed by the combination of rhIL-2 and IL7-Fc." (PMID 34440787, 2021). "Mice treated with CD3+CD34+ cells transduced following IL-7 culture demonstrated a significant delay in tumor progression when compared to untreated mice (p = 0.0025)." (PMID 34172810, 2021). "Overall, these data show that ARI2hIL-15 CAR-T cells have enhanced persistence and are superior to ARI2hIL-15/IL-7 CAR-T cells at preventing or reducing tumor growth in a MM murine model." (PMID 34298748, 2021). "IL-7 is the most important tumor immune-related cytokine in the γc family, and its function is mainly to regulate naive T cells and memory T cells homeostasis." (PMID 34386015, 2021). "For this experiment, NOD-SCIDIL2gc−/− mice that were previously engrafted with ARP-1-GFP cells until developing a high tumor burden were injected with untransduced (UT) T cells, ARI2hIL-15, ARI2hIL-2, or ARI2hIL-15/IL-7." (PMID 34298748, 2021). "Correspondingly, a recent publication found that IL-15-expanded CD19-CAR-T cells demonstrated enhanced anti-tumor efficacy compared to those cultured with IL-15/IL-7." (PMID 34298748, 2021). "Meanwhile, immune-stimulatory cytokines such as interleukin (IL)-7 play an important role in anti-tumor immunity." (PMID 34445415, 2021). "Recent studies, carried out on animal tumor models, show that different cytokines, including GM-CSF, IL-7, IL-12, IL-15, IL-18 and IL-21, are also able to limit tumor growth." (PMID 34208413, 2021).
tumor (continued). "When ARI2hIL-15, ARI2hIL-2 and ARI2hIL-15/IL-7 were rechallenged with tumor cells, they exhibited a more efficient cytotoxic functionality than after the first challenge but expanded slightly less." (PMID 34298748, 2021). "The cytotoxicity exhibited by ARI2hIL−15 against these tumor cells was similar to ARI2hIL-2 and ARI2hIL-15/IL-7 at effector:target (E:T) ratios ranging from 1:1 to 0.125:1." (PMID 34298748, 2021). "Our data suggest that IL7-Fc is principally beneficial for enhancing the efficacy of tumor-reactive T-cells in lymphopenic conditions for the ACT." (PMID 34440787, 2021). "Of interest, the concentration of IL-7 decreased with tumor stage, although significant differences in its expression were limited to metastasis and healthy donor groups." (PMID 33574842, 2021). "Upon development of palpable tumors (day 7 post injection), 5 × 106 CD3+CD34+ cells transduced either following IL-7 culture or CD3 activation were adoptively transferred intravenously into tumor-bearing mice." (PMID 34172810, 2021). "An autologous tumour vaccine modified with recombinant new castle disease virus to express IL-7 promotes anti-tumour immune responses in murine models by increasing the IFN-γ production and cytotoxicity of CD8+ T-cells." (PMID 34960140, 2021). "Pre-treatment with a subcutaneous administration of OVA-NPs deferred the progression of a thymic lymphoma, while OVA-NPs-IL-7 inhibited the proliferation of E.G7-OVA tumor cells." (PMID 34835555, 2021). "When the tumor-free mice inoculated with OVA-NPs-IL-7 plus EG.7 cells were rechallenged with E.G7-OVA cells, they displayed a decreased proliferation with respect to that in the control mice." (PMID 34835555, 2021). "Thymoquinone (Tq) treatment suppresses the activation of MMPs via IL-7/AKT/NF-κB signaling that inhibits IL-7-induced tumor progression and metastatic invasion in DU145 cells." (PMID 34768524, 2021). "Collectively, we conclude that IL7-Fc requires a lymphopenic condition to enhance the anti-tumor response in ACT using T cells." (PMID 34440787, 2021). "We discovered that CAR-T cells expanded with IL-15 had reduced dysfunction and enhanced persistence compared to those grown with IL-2 or a combination of IL-15 and IL-7, which resulted in longer and improved anti-tumor responses in a mouse model." (PMID 34298748, 2021). "In order to deliver supportive cytokines, we took advantage of the inherent ability of mesenchymal stem cells (MSCs) to actively migrate to tumor sites and engineered MSCs to release both IL7 and IL12 to promote homeostatic expansion and Th1 polarization." (PMID 32260097, 2020). "It is possible that the presence of IL-7 and IL-21 in the tumor microenvironment reduced CD5 by modulating transcriptional and/or posttranscriptional control mechanisms although that possibility is not specifically addressed by our data." (PMID 33584650, 2020). "It is clear that further studies will be needed to better clarify the role of IL-7 in tumor-progression." (PMID 32849527, 2020). "In this respect, data indicate that IL-7 administration following cyclophosphamide preconditioning supports the expansion of polyfunctional tumor-specific CD4 T cells." (PMID 32973794, 2020). "Caserta at al. reported that IL-7 was superior to IL-2 for expansion of tumour-reactive CD4+ T cells." (PMID 32183246, 2020). "In a transplanted xenograft tumor model, IL7/IL12 engineered MSCs boosted the anti-tumor activity of CAR T cells while non-modified MSCs do not have the effect." (PMID 32260097, 2020). "Nonetheless, the accumulating evidence presents IL-7 as a cytokine facilitating tumor growth and metastasis and aiding drug-resistance." (PMID 33020452, 2020). "A recent report demonstrated a local effect of IL7/12 engineered MSC on tumor infiltrating cells as well as a systemic effect on circulating lymphocytes resulting in up-regulation of activation markers." (PMID 32260097, 2020).
tumor (continued). "Taken together, CAR T cells and MSCs can mutually cooperate in enhancing a Th17 inflammatory anti-tumor response; IL7 and IL12 producing MSCs shift the T cell response to a Th1 like anti-tumor response." (PMID 32260097, 2020). "A fusion protein, IL-7-Fc, composed of a recombinant form of IL-7 and a hybrid Fc region of a human antibody has been shown to stimulate proliferation and survival of different T-cell subsets and enhance anti-tumor immune responses." (PMID 32849527, 2020). "In BC, IL-7 promotes tumor growth by activating the JAK1/3-STAT5 and PI3K/AKT pathways, while the IKZF1 gene plays important regulatory roles in lymphogenesis." (PMID 33164640, 2020). "In their study, cells cultured with IL-7 demonstrated greater anti-tumour potential upon adoptive transfer to tumour-bearing mice." (PMID 32183246, 2020). "IL-21/IL-7-treated cells have increased proliferation and production of inflammatory cytokines, directing improved lysis of tumor cells." (PMID 30842774, 2019). "IL-7 dependence on the location of the primary tumor should be taken into account in future IL-7-based immunotherapies." (PMID 31185636, 2019). "A xenograft model was established to assess the anti‐tumour efficacy of IL‐7 combining cisplatin in vivo." (PMID 31599032, 2019). "The adjuvant IL‐7 promoted the vaccine‐mediated anti‐tumour immunity with increased IL‐6 production and decreased T helper type 17 cell differentiations and enhanced CD8 T‐cell expansion." (PMID 31599032, 2019). "Materials and Methods: IL-7 was immunoenzymatically measured in paired surgical specimens of tumors and tumor-adjacent tissue (n = 48), and in the sera of 170 individuals (54 controls and 116 cancer patients)." (PMID 31185636, 2019). "The flavonoids of Hippophaerhamnoides L (TFH) isolated from berries of sea buckthorn up-regulated the levels of IL-1α, IL-2, IL-7, IL-15 etc. to activate NK cells and its cytotoxicity against tumor cells K562." (PMID 31138762, 2019). "Collectively, these data suggest that IL-7 and/or IL-7Rα are promising targets of inhibiting tumor metastasis." (PMID 31061414, 2019). "The concentrations of five cytokines out of 32 compounds analyzed on the array—IL-7, G-CSF, CCL11, LIF and VEGF—were higher in the tumor-associated adipose tissue than in normal mouse adipose tissue." (PMID 31752313, 2019). "Possible correlation between IL-7 overexpression, its concentration in tumor tissue and tumor-adjacent macroscopically normal tissue, and systemic concentrations of IL-7 were examined." (PMID 31185636, 2019). "Our group was first to report systemic IL-7 elevation in CRC in association with metastatic disease and tumor location, as well as cytokine association with bowel inflammation." (PMID 31185636, 2019). "Mature T cells also require IL-7 for survival, proliferation and multiple effector functions during infections and tumor infiltration." (PMID 31921158, 2019). "As IL-7 can augment the function of tumor-reactive CD8+ T cells, accumulating research has demonstrated recombinant IL-7 to be an adjuvant for adoptive immunotherapy." (PMID 31915416, 2019). "To exclude the effect of the IL-7 source on tumor growth in mice, we examined the effects of IL-7 from mice on human PC-3 cells." (PMID 31061414, 2019). "In vivo, cisplatin significantly inhibited tumour growth and IL‐7 combined with cisplatin achieved the best therapeutic effect." (PMID 31599032, 2019). "The mechanisms of TCM/chemotherapy combination involved with interleukin-7 (IL-7) potentially enhance immune responses against tumor." (PMID 31138762, 2019). "Numerous animal tumor models have demonstrated broad anti-tumor activity for various cytokines, including GM-CSF, IL-2, IL-7, IL-12, IL-15, IL-18 and IL-21." (PMID 31856922, 2019). "Further, in A549 cell transplanted model, treatment of IL‐7 combined with cisplatin also decreased the expression of Ki‐67 in tumour tissues and enhanced cell apoptosis induced by cisplatin in tumour tissues." (PMID 31599032, 2019).
tumor (continued). "IL-7 increased tumor sphere formation and expression of epithelial–mesenchymal transition (EMT) markers." (PMID 31061414, 2019). "The relation of IL-7 overexpression with cancer stage and lymph-node involvement lost its significance when coexamined with tumor location." (PMID 31185636, 2019). "Tumor location was a key determinant of IL-7 expression in the current study, both at the local and systemic level." (PMID 31185636, 2019). "This stromal IL-7 provides CD44-positive colon cancer cells with further increased tumor-initiating ability, thereby promoting tumor cell growth both in vitro and in vivo." (PMID 31067787, 2019). "Mean IL-7 concentration in tumor tissue was 64.8 pg/g (95% CI: 54.3–75.4), while in adjacent normal tissue it was 35.3 pg/g (26.5–44.1)." (PMID 31185636, 2019). "IL-7 alone increased the expression of GrB and Perforin to the same extent in tumor-infiltrating MAIT cells and their counterparts in the unaffected tissue, but did not lead to degranulation, as measured by CD107a." (PMID 31073372, 2019). "Various studies have shown the anti‐tumour activities of IL‐7 by regulating the immune responses against tumour." (PMID 31599032, 2019). "The goal of this study was to evaluate the anti‐tumour efficacy of interleukin‐7 (IL‐7) combining cisplatin against NSCLC." (PMID 31599032, 2019). "Of those, IL-7 in serum correlated positively with IL-7 concentration in tumor tissue, but only in patients with adenocarcinomas (ρ = 0.45, p = 0.013)." (PMID 31185636, 2019). "The overexpression of IL-7 in tumor tissue as compared to patient-matched normal tissue was significantly stronger in Stage 3/4 (T3/4) cancers than in less advanced Stage 1/2 (T1/2) cancers." (PMID 31185636, 2019). "In this study, CcR expression induced phosphorylation of STAT5 (part of the native signaling cascade in IL7 signaling) after ligation with tumor-secreted IL4, and restored T cell proliferation in the presence of the cytokine." (PMID 31024832, 2019). "In A549/DDP cell transplanted model, IL‐7 combined with cisplatin significantly suppressed the tumour growth compared with cisplatin treatment." (PMID 31599032, 2019). "Corresponding with its protective role against infection, IL-7 concentrations in both normal and tumor tissue were the highest in the colon, a part of gastrointestinal tract with the highest exposure to bacteria." (PMID 31185636, 2019). "Given its role in immunity and the pathogenesis of neoplasia, it was opted to explore IL-7's role in the multidrug resistance of DDP in NSCLCs." (PMID 31915416, 2019). "The overexpression of IL-7 in tumor tissue as compared to patient-matched normal tissue was significantly stronger in patients with cancers with lymph-node metastasis (N1) than in those without (N0)." (PMID 31185636, 2019). "MUC-1-specific CAR T cells have been engineered with a switch receptor containing an IL-4 ectodomain and an IL-7 endodomain to counter the IL-4-rich tumor microenvironment." (PMID 30842774, 2019). "We evaluated the potential of using an IL-7 blocking antibody (Ab) and a Janus kinase (JAK) inhibitor to control IL-7-induced tumor cell migration and invasion." (PMID 31061414, 2019). "This therapeutic intervention substantially inhibited tumor growth indicating that Il7-expressing CAFs are important for BC propagation." (PMID 29632733, 2018). "Specifically, we found that targeted ablation of Cxcl12 in Il7-Cre+ stromal cells abrogates the tumor-initiating potential of BC cells and that this niche dependence can be therapeutically harnessed through antagonism of CXCR4." (PMID 29632733, 2018). "We found that fibroblasts expressing the Cre recombinase under the control of the interleukin 7 promoter occupied mainly the tumor margin where they physically interacted with tumor cells." (PMID 29632733, 2018). "In vivo ablation of Il7-expressing CAFs inhibited tumor growth and depleted the pool of clonogenic (stem-like) cancer cells." (PMID 29632733, 2018).
tumor (continued). "Ki-67 staining demonstrated in situ proliferative potential of Il7-expressing PDPN+ CAFs suggesting that the cells are engaged in dynamic cellular interactions in the tumor margin." (PMID 29632733, 2018). "Previous mouse and human studies showed that IL-7 can support immune cell reconstitution in lymphopenic conditions, expand tumor-reactive T cells for adoptive immunotherapy, and enhance effector cytokine expression by autoreactive T cells." (PMID 29506153, 2018). "We previously found that IL-7 selectively expands tumor-reactive CD4 T cells capable of promoting tumor protection in ACT." (PMID 29506153, 2018). "In the setting of adoptive T-cell therapy (ACT), IL-7 has been used in primary cultures to engineer and expand tumor-reactive T cells." (PMID 29506153, 2018). "In a previous mouse study, we found that IL-7 favored the in vitro expansion of tumor-Ag-experienced T cells, by promoting their proliferation." (PMID 29506153, 2018). "IL-7 supports host immunity in lymphopenic and immunosuppressed patients and expands tumor-reactive T cells for adoptive immunotherapy." (PMID 29506153, 2018). "Given that IL-7Rα expression is regulated by both TCR and IL-7 signaling, we went on to delineate the impact of TCR and/or IL-7 signaling on the IL-7 responsiveness of tumor-specific CD4+ T cells as well as bystander T cells." (PMID 28939858, 2017). "In a mouse model of tumor vaccination, recombinant IL-7 boosted CD4 T cell function and overcame the inhibitory network imposed by the suppressive tumor microenvironment." (PMID 29272267, 2017). "In the setting of ACT, IL-7 as a T cell growth factor has been used in ex vivo cell culture to expand tumor-reactive T cells." (PMID 28939858, 2017). "We and others demonstrated that tumor-reactive CD4+ T cells expanded in vitro in the presence of IL-7 exhibit superior antitumor potency upon adoptive transfer." (PMID 28939858, 2017). "It is conceivable that in the setting of ACT, tumor-specific CD4+ T cells would receive antigenic stimulation while being exposed to increased levels of endogenous IL-7." (PMID 28939858, 2017). "We suspected that depleting IL-7 would decrease engraftment of the donor cells and impair their control of tumor growth." (PMID 29033940, 2017). "Even at a decreased dose of lymphocytes (10 million cells/mouse) the IL-2, IL-21, IL-2/21, IL-7/15 and IL-7/15/21 groups were significantly better at slowing or decreasing tumor growth than the control or the cyclophosphamide-alone groups (all p < 0.0001)." (PMID 28146052, 2017). "Not only does IL-1B appear positively correlated with MAP17 in all tumors, other interleukins including IL-15, IL-18, IL-1A, IL-32 and IL-7 and interleukin receptors including IL-10RB, IL-17RC and IL-2RG appear in at least three of the tumor types." (PMID 29228712, 2017). "Tumor samples were harvested 3 h after intratumoral injections for the analysis of IL-7 (CD45.1) effectors." (PMID 28496990, 2017). "Alternatively, tumor-specific donor T cells can be engineered to overexpress IL-7Rα to allow them respond to exogenous IL-7 after transfusion." (PMID 28939858, 2017). "Although functional data are still scanty, available evidence seems to link IL-7 overexpression with tumor aggressiveness, metastasis, and unfavorable prognosis." (PMID 27866242, 2017). "The relevance of cytokine serum elevation found in cancer or the role of IL-7 expression and secretion by tumor cells remains elusive." (PMID 27866242, 2017). "IL-7 preferentially increases number of recent thymic emigrants, naïve, and central memory T cells as well as tumor-redirected cytotoxic T lymphocytes." (PMID 27866242, 2017). "Tumor-reactive murine CD8 αβ T cells expanded ex vivo using IL-15 or IL-7/IL-15 mediate increased tumor immunity in vivo as compared to cells grown in IL-2." (PMID 28239463, 2017). "IL-7 and IL-15 mediated TCR sensitization enables T cell responses to self-antigens such as tumor associated antigens." (PMID 28477011, 2017).